GLA (galactosidase alpha)
Diseases named in the same sentence as GLA in open-access papers (continued):
Sharing a sentence is not in itself a finding about the gene and the disease.
Fabry disease (continued). "This study is the first to report a novel loss-of-function mutation, p.Asn278Lys, in exon 6 of the GLA gene as a genetic aetiology for Fabry disease." (PMID 30587147, 2018). "Fabry disease (OMIM 301500) is an X-linked storage disorder with mutations affecting the α-galactosidase A gene (GLA, α-GalA, E.C. 3.2.1.22) which encodes for α-GalA." (PMID 30261035, 2018). "Although the alternatively spliced transcript is reported to be responsible for the reduced enzyme activity causing Fabry disease, the mechanism of GLA splicing is unclear." (PMID 28430823, 2017). "The presence of Fabry disease was defined by abnormal alpha-galactosidase A activity in males or alpha-galactosidase gene (GLA) mutation in females." (PMID 28871487, 2017). "Fabry disease (FD) is an X-linked lysosomal disorder caused by a deficiency of α galactosidase A (GLA), due to mutations in the GLA gene at Xq22." (PMID 28430823, 2017). "With the advancement of molecular diagnostic tools, more disease-causing mutations in α-galactosidase A (GLA) have been identified in Fabry disease." (PMID 27776503, 2016). "Fabry disease is caused by mutations in the α-galactosidase A (GLA) gene, which is located in X-chromosome coding for the lysosomal enzyme of GLA." (PMID 27160240, 2016). "The mechanisms underlying the upregulation and elevated secretion of IL-18 in FC-iPSC-CMs were assessed, and one of possible cause was the reduced expression and activity of GLA in Fabry disease." (PMID 27888626, 2016). "A novel GLA mutation, c.263A > G (p.Tyr88Cys), was found in a Korean family with predominant renal manifestations of Fabry disease." (PMID 27776503, 2016). "Fabry disease (FD) is a rare X-linked recessive genetic disorder caused by a deficient activity of the lysosomal enzyme alpha-galactosidase A (GLA)." (PMID 28933415, 2016). "Fabry disease is caused by mutations in the GLA gene and is characterized by a large genotypic and phenotypic spectrum." (PMID 27916943, 2016). "A high incidence of GLA IVS4+919 G>A mutation in patients with Fabry disease of the later-onset cardiac phenotype, has been reported in Taiwan." (PMID 27888626, 2016). "Fabry disease is caused by deficiency of the lysosomal enzyme alpha-galactosidase A, coded by GLA gene on Xq21.3-q22." (PMID 27992580, 2016). "Fabry disease (FD), secondary to a deficit in α-galactosidase A caused by abnormalities in the GLA gene, belongs to X-linked lysosomal disorders." (PMID 25997047, 2015). "Fabry disease (FD) due to mutations in the GLA gene has been suggested as an underdiagnosed cause of stroke, and one feature is SVD." (PMID 26305465, 2015). "In Fabry disease, mutations in the α-galactosidase A (GLA) gene cause functional deficiency of the enzyme α-GLA." (PMID 26416388, 2015). "Accumulation of galactosphingolipids is a general characteristic of Fabry disease, a lysosomal storage disorder caused by the deficient activity of α-galactosidase A encoded by the GLA gene." (PMID 26334996, 2015). "Fabry disease is a lysosomal storage disease caused by enzyme α-galactosidase Adeficiency as a result of mutations in the GLA gene." (PMID 26269958, 2015). "Fabry disease is caused by deficient activity of α-galactosidase A (GLA) and characterized by systemic accumulation of glycosphingolipids, substrates of the enzyme." (PMID 26661087, 2015). "Another monogenic disorder that causes SVD is Fabry disease (FD), an X-linked lysosomal storage disorder, caused by mutations in the GLA gene." (PMID 26305465, 2015). "Fabry disease is an X-linked inherited metabolic condition where the deficit of the α-galactosidase A enzyme, encoded by the GLA gene, leads to glycosphingolipid storage, mainly globotriaosylceramide." (PMID 24398019, 2014). "A deficiency of alpha-galactosidase A (GLA, E.C.3.2.1.22) leads to Fabry disease (FD), an X-linked lysosomal storage disorder." (PMID 25423912, 2014).
Fabry disease (continued). "Still, recent data has also revealed the presence of overt Fabry’s disease in females with heterozygous mutations in the GLA gene." (PMID 23691056, 2013). "So far, more than 600 genetic mutations causing Fabry disease have been identified, and it is known that gross alterations, nonsense mutations, and most of the splicing mutations of the GLA gene lead to the classic form." (PMID 24386359, 2013). "Missense mutations in the α-galactosidase A (GLA) gene comprising the majority of mutations responsible for Fabry disease result in heterogeneous phenotypes ranging from the early onset severe “classic” form to the “later-onset” milder form." (PMID 24386359, 2013). "Deficiency in GLA activity causes systemic accumulation of glycolipids, predominantly globotriaosylceramide (Gb3), and leads to the X-linked genetic disorder Fabry disease (OMIM 301500)." (PMID 24236025, 2013). "Anderson Fabry disease (FD) (OMIM 301500) is an X-linked inherited sphingolipid storage disorder caused by deficiency of lysosomal enzyme alpha-galactosidase A (GLA)." (PMID 24207059, 2013). "Anderson-Fabry disease (Fabry disease) is an X-linked inherited lysosomal storage disorder which leads to a deficiency of a functionally active enzyme (α-galactosidase A – GLA) as a result of a defect in the GLA-gene." (PMID 24015197, 2013). "In Fabry’s disease a mutation in the gene encoding α-galactosidase A (α-Gal A) on the X chromosome (GLA gene) leads to deficiency or impaired function of this lysosomal enzyme." (PMID 23691056, 2013). "Pathogenic GLA mutations cause Fabry disease, a vascular endothelial glycosphingolipid storage disease typically presenting with a symptom complex of renal, cardiac, and cerebrovascular manifestations." (PMID 23393592, 2013). "Fabry disease (MIM 301500) is an X-linked genetic disorder resulting from a deficiency of α-galactosidase A (GLA; EC 3.2.1.22) activity." (PMID 24386359, 2013). "Fabry disease (FD) is an X-linked lysosomal storage disease secondary to deficiency of the lysosomal enzyme alpha-galactosidase A (GLA) where globotriaosylsphingosine (Gb3) – the primary GLA substrate – accumulates in a variety of tissues." (PMID 22558451, 2012). "Fabry disease (FD) is caused by a deficiency of the lysosomal enzyme alpha-galactosidase A (GLA) resulting in the accumulation of globotriaosylsphingosine (Gb3) in a variety of tissues." (PMID 22558451, 2012). "Fabry disease (FD) is a hereditary metabolic disorder caused by the partial or total inactivation of a lysosomal hydrolase, the enzyme α-galactosidase A (GLA)." (PMID 22682330, 2012). "Fabry disease (OMIM 301500) is a rare X-linked inherited lysosomal storage disorder caused by deficient enzymatic activity of α-galactosidase A (GLA)." (PMID 21698285, 2011). "Fabry disease (FD) (OMIM 301500) is an X-linked lysosomal storage disorder due to a deficiency of the enzyme alpha-galactosidase A (GLA)." (PMID 20478016, 2010). "This method was applied to detect globotriaosylceramide (Gb3) accumulation in the heart tissue of murine models of Fabry disease, including mice deficient in α-galactosidase A (GLA) activity (GLA knockout) and transgenic mice with a GLA knockout and an upregulation of Gb3 synthase." (PMID 42242673, 2026). "Fabry disease is an X‐linked lysosomal disease caused by variants in the GLA gene." (PMID 39822326, 2025). "This was found for patients with Fabry disease, where females are heterozygous for the lysosomal enzyme agalactosidase A (GLA) mutation or experience X-chromosome inactivation, and they may be asymptomatic or have only mild symptoms." (PMID 40150443, 2025). "Fabry disease (FD) is a lysosomal storage disorder caused by pathogenic variants in the GLA gene." (PMID 41171941, 2025).
Fabry disease (continued). "The results reported here provide substantial evidence that the novel c.484delT variant in the GLA gene is causative of the classic form of Fabry disease in the two patients who presented with reduced enzyme activity, accumulation of Lyso-Gb3 and classic signs of the disease." (PMID 39859185, 2025). "Fabry disease is a rare lysosomal storage disorder caused by a deficient or markedly reduced activity of the lysosomal enzyme α-galactosidase A (α-Gal A), encoded by the GLA gene located on the X chromosome." (PMID 41465551, 2025). "Fabry disease (FD) is a rare X-linked lysosomal storage disorder caused by mutations in the GLA gene, leading to α-galactosidase A deficiency and subsequent accumulation of glycosphingolipids, including globotriaosylceramide (Gb3) and globotriaosylsphingosine (lyso-Gb3), in multiple organs." (PMID 40299366, 2025). "Fabry disease is a multisystemic lysosomal disorder caused by mutations in the GLA gene." (PMID 40948726, 2025). "In this study, we report a novel pathogenic variant, identified through the sequencing of the GLA gene, in two members of a family who presented classic clinical manifestations of Fabry disease, reduced enzyme activity and the presence of elevated Lyso-Gb3 in the blood." (PMID 39859185, 2025). "Fabry disease (FD) is an inherited X-linked disorder characterized by a deficiency of the lysosomal enzyme α-galactosidase A (α–Gal A) (EC entry 3.2.1.22) due to mutations in the GLA gene (Gene Entrez: 2717; NCBI reference: NM_000169.3; OMIM #3006440)." (PMID 40072051, 2025). "These novel findings may assist in the diagnosis of Fabry disease and enhance the clinical and molecular understanding of the correlations between variants in the GLA gene and the Fabry phenotype." (PMID 39859185, 2025). "This vector encodes the human alpha-galactosidase A (GLA) gene and could provide a potential long-term treatment option for patients with Fabry disease that may be superior to existing enzyme replacement therapy (ERT)." (PMID 39845823, 2024). "Fabry disease is a rare X-linked lysosomal storage disorder that leads to the accumulation of globotriaosylceramide (Gb3) across various tissues, stemming from a deficiency in alpha-galactosidase A (GLA)." (PMID 39092329, 2024). "Both these tests could lead to missed diagnoses of Fabry disease in female patients, so the analysis of the GLA gene represents the main diagnostic test for Fabry disease in women to date." (PMID 38791200, 2024). "Fabry disease (FD) is a rare X-linked inherited lysosomal storage disorder characterized by a deficiency of α-galactosidase A (GLA), resulting from mutations in the GLA gene." (PMID 39650153, 2024). "Background/Objectives: Fabry disease (FD) is a genetic lysosomal storage disease caused by a pathogenic variant in GLA gene coding for a functional alpha-galactosidase A enzyme whose disfunction leads to globotriaosylceramide (Gb3) accumulation in cells, which results in multiple organ disorders." (PMID 39685527, 2024). "Fabry disease is an XL disorder caused by pathogenic variants in GLA which encodes α-galactosidase." (PMID 37578539, 2024). "Fabry disease is an inherited X-linked disease caused by mutations in the GLA gene." (PMID 39119442, 2024). "Also, recent interest in complex and systemic lysosomal storage diseases, such as Fabry disease, has highlighted GLA mutations as possible causes of FSGS." (PMID 37728640, 2024). "Fabry disease is a recessive lysosomal storage disease, linked to the X chromosome, due to the deficiency of the enzyme α-galactosidase A (α-Gal A), which is secondary to the GLA gene mutation." (PMID 38279275, 2024). "Fabry disease is a rare X-linked lysosomal storage disorder caused by mutations in the galactosidase alpha (GLA) gene, resulting in the accumulation of globotriaosylceramide (Gb3) and its deacetylated form, globotriaosylsphingosine (Lyso-Gb3) in various tissues and fluids throughout the body." (PMID 39596318, 2024).
Fabry disease (continued). "Anderson-Fabry disease is a rare lysosomal storage disease caused by deficiency in alpha-galactosidase-A due to mutations in the GLA gene, leading to accumulation of glycosphingolipids in vital organs including the nervous system, gastrointestinal system, kidneys, and heart." (PMID 38495661, 2024). "Fabry disease is a rare multisystem metabolic disease resulting from multiple types of mutations in the GLA gene that cause deficiency of the lysosomal enzyme alpha-galactosidase A, resulting in accumulation of glycosphingolipids, particularly globotriaosylceramide, in the lysosomes leads to (GL3)." (PMID 37213895, 2023). "Fabry disease is caused by mutations in the GLA gene leading to a deficiency of the α-Galactosidase An enzyme, causing the accumulation of globotriaosylceramide (known as Gb3 or CD77), a glycosphingolipid functioning as a receptor for pathogens and pathogenic products." (PMID 37601653, 2023). "Fabry disease (FD) is a rare X-linked storage disorder resulting from deficient activity of lysosomal hydrolase α-galactosidase A (α-Gal A) caused by genetic defects in the GLA gene." (PMID 37480128, 2023). "For Fabry disease, six clinical trials of AAVs encoding the GLA gene are currently ongoing." (PMID 36835039, 2023). "Fabry disease (FD) is an X-linked condition caused by variants in the GLA gene." (PMID 36624527, 2023). "Fabry disease is caused by mutations in the alpha-galactosidase A gene (GLA)." (PMID 37510112, 2023). "Preclinical studies of AAV6 encoding the human GLA gene were conducted in mice with Fabry disease." (PMID 36835039, 2023). "Fabry disease (FD) is an X-linked lysosomal storage disorder (LSD) secondary to mutations in the GLA gene that causes dysfunctional activity of lysosomal hydrolase α-galactosidase A and results in the accumulation of globotriaosylceramide (Gb3) and globotriaosylsphingosine (lyso-Gb3)." (PMID 36982318, 2023). "Fabry disease is an x-linked inherited multisystem lysosomal disorder that leads to insufficient activity of the lysosomal enzyme α-galactosidase due to abnormalities of the responsible GLA gene, which controls its synthesis." (PMID 36123734, 2022). "Through newborn screening and related genetic tests, our study team and other researchers have reported a high prevalence (1 in 600 to 1250 people) of a pathogenic variant of late-onset cardiac Fabry disease (IVS4 + 919 or c.926 + 919G > A of the GLA gene) in the Taiwanese population." (PMID 36556012, 2022). "A few countries perform newborn screening, which has resulted in disclosing many variants of unknown significance in the GLA gene and only few patients with classical Fabry disease." (PMID 36383556, 2022). "The clinical manifestations of Fabry disease are mainly caused by functional defects in the GLA enzyme, which may lead to progressive accumulation of Gb3 in lysosome-containing cells, including the vascular endothelium, smooth muscle cells, and cardiomyocytes." (PMID 36556012, 2022). "Fabry disease is a X-linked lysosomal storage disorder caused by enzyme α-Galactosidase A (α-Gal A) deficit due to GLA gene mutations, leading to progressive tissue accumulation of glycosphingolipids, especially globotriaosylceramide (Gb3) and globotriaosylsphingosine (lyso-Gb3)." (PMID 35548424, 2022). "Fabry disease (FD) is an X-linked lysosomal storage disorder (LSD) caused by mutations in the GLA gene, leading to a deficiency of α-galactosidase A (α-gal A; EC 3.2.1.22) and resulting in the storage of globotriaosylceramide (GL3) and related lipids in the lysosome." (PMID 34362157, 2021). "Recent studies on α-galactosidase A (GLA) deficiency, causing the rare X-linked LSD Fabry disease, suggest there may be an increased risk of developing PD in GLA mutation-positive individuals." (PMID 34149605, 2021).
Fabry disease (continued). "Fabry disease is an X-linked lysosomal storage disorder caused by mutations in the α-galactosidase A (GLA) gene that result in deficient α-galactosidase A (α-Gal A) enzyme and the accumulation of globotriaosylceramide (Gb3) and associated glycosphingolipids throughout the body." (PMID 34204530, 2021). "Fabry disease (FD) is an X-linked lysosomal storage disorder caused by mutations of the GLA gene that result in a deficiency of the enzymatic activity of α-galactosidase A and consequent accumulation of glycosphingolipids in body fluids and lysosomes of the cells throughout the body." (PMID 33922740, 2021). "Fabry disease (FD) is the second most frequent lysosomal storage disorder caused by a progressive accumulation of globotriaosylceramide (Gb3) in body fluids and tissues due to deficient α-galactosidase A (GLA) activity." (PMID 33673551, 2021). "Fabry disease (FD) is an X-linked lysosomal disease caused by pathogenic variants of the GLA gene, which encode a defective alpha-galactosidase A enzyme, contributing to substrate accumulation in several organs, with varying degrees of severity and subsequent loss of organ function." (PMID 34287477, 2021). "Mutations of GLA are mainly associated with Fabry disease, an X-linked disease." (PMID 33946922, 2021). "Fabry Disease (FD), a rare and progressive, X-linked lysosomal storage disorder, is caused by mutations in the α-galactosidase A (GLA) gene which leads to enzymatic deficiency of GLA." (PMID 33634157, 2021). "Fabry disease is caused by a pathogenic mutation in the GLA gene." (PMID 32295281, 2020). "Fabry disease (FD) is a rare X-linked lysosomal storage disorder, caused by deficiency of the enzyme α-galactosidase A (GLA), resulting in an accumulation of globotriaosylceramide in tissues, mainly heart, brain and kidney, leading to progressive organ dysfunction." (PMID 33036343, 2020). "This is in agreement with a recent report on the structural basis of Fabry disease, in which the wANNOWAR software was tested for its accuracy in predicting the pathogenicity of several variants (already described and proved to be pathogenic) in the GLA gene." (PMID 32883051, 2020). "There are more than 1000 mutations in the GLA gene known to be associated with Fabry disease." (PMID 33036426, 2020). "Mutations in GLA cause Fabry disease (MIM:301500), a rare genetic condition." (PMID 30995449, 2019). "Pathogenic variants in the GLA gene cause Fabry disease, a lysosomal storage disorder characterised by neuropathic pain, angiokeratoma, chronic kidney disease, left ventricular hypertrophy (mimicking hypertrophic cardiomyopathy (HCM)), and cerebrovascular disease." (PMID 30847665, 2019). "Fabry disease is caused by pathogenic mutations in GLA gene causing enzymatic deficiency of alpha-galactosidase A leading to accumulation of globotriaosylceramide (Gb3) and lyso-Gb3 not limited to lysosomes but also in plasma membranes and caveolae of endothelial cells." (PMID 31150494, 2019). "Fabry disease is caused by loss of activity of the lysosomal hydrolase α-galactosidase A (GLA)." (PMID 31120949, 2019). "Fabry disease is a rare X-linked multiorgan disorder caused by mutations of the GLA gene that encodes alpha-galactosidase A, deficient activity of which results in the accumulation of globotriaosylceramide in lysosomes in multiple cell types throughout the body." (PMID 31593141, 2019). "Based on the implications of this initial signal, future studies should focus on larger cohorts, in-person examination of individuals with Fabry disease by a movement disorders neurologist, and related biomarker studies including alpha-galactosidase A activity and GLA mutation analysis." (PMID 29159076, 2018). "In fact, the phenotype associated with the adult onset of Fabry disease might be rather common with different mutations in the GLA gene in other areas." (PMID 30211004, 2018).